CD34 (CD34 molecule)
Diseases named in the same sentence as CD34 in open-access papers (continued):
Sharing a sentence is not in itself a finding about the gene and the disease.
plasma cell neoplasm (4 papers, 2020 to 2025). A clonal proliferation of immunoglobulin-secreting plasma cells. "Considering the pathophysiology of plasma cell neoplasms, it has been evident that during differentiation and maturation of B cells, early B cell precursors express TdT, CD34 and HLA-DR." (PMID 33418558, 2021).
preeclampsia (4 papers, 2019 to 2024). Preeclampsia is a hypertensive disorder of pregnancy that is characterized by new-onset hypertension with proteinuria presenting after 20 weeks of gestation, and depending on mild or severe forms may initially present with severe headache, visual disturbances, and hyperreflexia. "Over 20 weeks gestation, women with preeclampsia showed a high level of Endothelial progenitor cells (CD34+) than the normotensive women." (PMID 34867473, 2021). "The EPC circulating in maternal blood is characterized by CD34 antigen expression, and is used as a preeclampsia marker, related to vascular wound healing, and detected in pathological placenta." (PMID 34867473, 2021). "Although the expression of CD117 cells in UCB-MNC was relatively low, its expression in UCB-enriched CD34+ cells were high, up to 50 and 20% for the control and preeclampsia group, respectively." (PMID 32650736, 2020). "This explains the low expression of CD34+ cells in UCB-MNC, where the expression level for CD34+ cells was 7% and less than 2% in the control and preeclampsia group, respectively." (PMID 32650736, 2020). "Both groups showed a significant correlation between low UCB volume and reduced TNC (Control p = < 0.0005; Preeclampsia p = < 0.0005) and total CD34+ cells (Control p = < 0.0005; Preeclampsia p = 0.001)." (PMID 32650736, 2020). "Presumably, these eminent CD34+ cells have high potential to differentiate into HSC colonies compared to the preeclampsia group, although the same number of seeding was performed initially." (PMID 32650736, 2020). "The higher number of haematopoietic colonies in the control group also indicated that the CD34+ cells were able to differentiate and proliferate, suggesting that these cells were better compared to those in the preeclampsia group." (PMID 32650736, 2020). "CD34+ enriched cells from both the preeclampsia and control groups were differentiated into haematopoietic colonies or lineages." (PMID 32650736, 2020). "The expression of CD34 and CD133 markers decreased to less than 10% while the expression of CD16 and CD3 increased in the control group compared to the preeclampsia group." (PMID 32650736, 2020). "In a previous study performed by our group, we have confirmed that preeclampsia did affect the quality of UCB-HSC in terms of TNC and CD34+ cell counts." (PMID 32650736, 2020). "The HSC markers expression in both the preeclampsia and control groups for UCB-MNC (pre-enriched samples), UCB enriched CD34+ cells (post-enriched samples) and differentiated haematopoietic cells (post-enriched and CFU assay) were compared." (PMID 32650736, 2020). "In this study, the quality and potency of NCC, CD34+ cells, and endothelial progenitor cells from HSC UCB will be further investigated in pregnant mothers with preeclampsia." (PMID 32650736, 2020). "Although there was a slight increment of CD45 expression in the UCB-enriched CD34+ cells in the preeclampsia group, this phenomenon has never been discussed before in any study or review." (PMID 32650736, 2020). "In contrast, there was a non-significant trend toward decreased CD34+ with preeclampsia, a finding that supports previous studies in preeclamptic pregnancies." (PMID 31799226, 2019).
renal fibrosis (4 papers, 2016 to 2024). A final common manifestation of a wide variety of chronic kidney diseases characterized by glomerulosclerosis and tubulointerstitial fibrosis. "The loss of peritubular capillaries, indicated by decreased CD34 expression, was an independent predictor of renal fibrosis in DN patients and animal models." (PMID 34671682, 2021). "Since it has been demonstrated that TGF‐β1 stimulates miR‐382‐5p expression during renal fibrosis, we investigated whether it could be able to regulate the miR‐382‐5p expression in normal CD34+ cells." (PMID 30259659, 2018). "Together with our observation that CD34 and A1AR were adjacent to each other in the renal peritubular microenvironment in DN patients, it is a reasonable assumption that A1AR might attenuate renal fibrosis by protecting vascular endothelial cells in DN." (PMID 34671682, 2021). "Notably, the development of renal fibrosis coincided with the upregulation of MCP‐1 and infiltration of monocytic CD34+ fibroblast precursors, which were absent at 1 week." (PMID 27125666, 2016).
small bowel tumor (4 papers, 2016 to 2025). "These consistent patterns support the external validity of our findings and highlight the diagnostic value of integrating CD117, DOG1, CD34, and Ki-67 in the assessment of small bowel tumors." (PMID 41465833, 2025). "While, most of the stomach GISTs were negative for ASMA (70.8%) and S-100 (64.3%) and positive for CD34 and CD117 (as well as most of small intestine tumors were positive for both), most of the large intestine GISTs were seen to be positive for ASMA (26.3%) and negative for CD34 (41.7%)." (PMID 29996918, 2018).
T-cell leukemia (4 papers, 2010 to 2025). A malignant disease of the T-lymphocytes in the bone marrow, thymus, and/or blood. "We tested four common methods of RNA-seq library preparation, using ribosomal RNA-depleted RNA from either human Jurkat T-cell leukemia cells or primary human CD34+ hematopoietic progenitor cells from normal donors." (PMID 28459821, 2017).
thrombosis (4 papers, 2018 to 2026). "In both LEDVT patients and LEDVT modeled mice, the CD31+CD34+ cells in peripheral blood had increased dramatically and recruited to the venous thrombosis, which will help in recanalization of the thrombus." (PMID 30287499, 2018). "Specifically, thrombosis occurrence was not available in this cohort, and we note that circulating CD34-positive cell quantification may also be of interest for assessing thrombotic risk, given the potential link between increased progenitor cell mobilization and vascular complications." (PMID 41540281, 2026).
thyroid cancer (4 papers, 2011 to 2026). "In well differentiated thyroid carcinoma immunostaining of blood vessels by CD34 displayed vasculature in close association with epithelial cancer cells." (PMID 21811634, 2011). "Contrary to BCCs, in a number of more biologically aggressive carcinomas—including breast, lung, colon, prostate, pancreas, and thyroid cancers—as well as in some benign lesions such as benign prostatic hyperplasia, “recruitment” of CD34-immunoreactive fibroblasts into tumor stroma occurs." (PMID 41597444, 2026). "CD34 plays as a role in response to iodine-131 radiotherapy in thyroid carcinoma." (PMID 33363022, 2020).
trichoepithelioma (4 papers, 2011 to 2026). "Kirchmann highlighted the differential diagnostic significance of the CD34 expression pattern in BCC versus trichoepithelioma, reporting that, compared with BCCs, neoplastic nests of trichoepithelioma are surrounded by CD34-immunopositive stroma." (PMID 41597444, 2026). "To establish the characteristics of CD34+SCs/TCs in the stroma of these tumors, we will use trichoepithelioma as an example." (PMID 34298962, 2021). "In trichoblastoma, trichofolliculoma, trichoadenoma and trichoepithelioma, stromal cells expressing CD34 were observed adjacent to the external surface of tumoral islands." (PMID 34298962, 2021). "Next, we will consider CD34+SC/TC behavior in trichoepithelioma and in the nevus sebaceous of Jadassohn as examples of this group of lesions." (PMID 34298962, 2021). "CD34 was shown to be strongly expressed in the tumor-associated stroma of trichoepithelioma and absent or only focal in the dermis surrounding the nests of BCCs." (PMID 21152127, 2011).
tuberculosis (4 papers, 2019 to 2022). A chronic, recurrent infection caused by the bacterium Mycobacterium tuberculosis. "Our aim was to determine whether M tuberculosis complex DNA is detectable in CD34-positive peripheral blood mononuclear cells (PBMCs) isolated from asymptomatic adults living in a setting with a high tuberculosis burden." (PMID 34100007, 2021). "We therefore aimed to determine whether M tuberculosis complex DNA could be detected in CD34-positive and CD34-negative peripheral blood mononuclear cells (PBMCs) isolated from a heterogeneous group of asymptomatic adults in whom active tuberculosis had been excluded." (PMID 34100007, 2021).
ulcerative colitis (4 papers, 2011 to 2023). An inflammatory bowel disease involving the mucosal surface of the large intestine and rectum. "CD34 has been used as a marker of TCs; the number of CD34+ TCs in the intestine of rats with ulcerative colitis is significantly decreased, and it gradually increases after drug treatment and the consequent improvement of the symptoms." (PMID 37051017, 2023). "Interestingly, the expression of CD34 in ulcerative colitis and Crohn’s disease is also correlated." (PMID 37051017, 2023). "CD34 enhances the migration ability of eosinophils, since those lacking CD34 have impaired migration, and the symptoms of ulcerative colitis are consequently alleviated." (PMID 37051017, 2023).
ulcers (4 papers, 2012 to 2019). "Thus, it can be hypothesized that wound healing requires early release of CD34+KDR+ cells from the bone marrow while the subsequent observed reduction could be associated with homing of these cells to the ulcer area." (PMID 24358275, 2013). "The degree of neovascularisation (angiogenesis), assessed by specific endothelial markers including von Willebrand Factor VIII, CD31, and CD34 in experimental ulcer models correlates well with the extent and speed of ulcer healing." (PMID 22966242, 2012). "CD34+KDR+ cells were increased in DFU patients when compared to at risk of DFU patients and were reduced at the end of the study in patients who healed their ulcers." (PMID 24358275, 2013). "In the PROVASA trial, patients with healing ulcers after IA BM-MNC application had received a greater number of total BM-MNCs, as well as of CD34+ cells." (PMID 27530339, 2016).
Wilms tumor (4 papers, 2013 to 2024). An embryonal neoplasm characterized by the presence of epithelial, mesenchymal, and blastema components. "And immunohistochemistry showed that vimention and CK (AE1/AE3) were positive, and Bcl‐2, CD34, CK20, SMA, and WT1 (Wilms' tumor) were negative." (PMID 38767517, 2024).
abscess (3 papers, 2009 to 2025). An inflammatory process characterized by the accumulation of pus within a newly formed tissue cavity which is the result of a bacterial, fungal, or parasitic infection or the presence of a foreign body. "On immunohistochemical staining with CD34 antibody, avascular areas (abscess, necrosis, hemorrhage) in POP were identified in 13/31 cases (41.9%) with an inhomogeneous enhancement on CEUS." (PMID 34573943, 2021). "We investigated the effect of NO-np on angiogenesis in MRSA abscesses by measuring the expression of CD34." (PMID 19915659, 2009). "This case is notable for its initial presentation mimicking cellulitis and abscess formation, diverting early suspicion from a hematologic origin.The diagnosis of MS requires histopathologic confirmation with immunohistochemical staining for markers such as CD34, CD43, and MPO." (PMID 41194805, 2025). "In this regard, tissue sections stained for CD34, a marker for blood vessel formation, demonstrated that NO-np reduces angiogenesis in MRSA abscesses." (PMID 19915659, 2009).
acute megakaryocytic leukemia (3 papers, 2014 to 2022). "Imatinib produced no measurable effect in the CD34+ cells from primary acute megakaryocytic leukemia at therapeutically relevant concentrations (IC50, >5 μmol/l)." (PMID 24527087, 2014).
alcoholic hepatitis (3 papers, 2022). Acute hepatitis resulting from ingestion of alcohol. "Positive CD34+ with ASGPR (heavy alcoholic hepatitis) or CK18 (alcoholic hepatitis) in EVs can be used as biomarkers, among them, CD34 can also be used as a biomarker to determine heavy alcoholic hepatitis." (PMID 35692794, 2022). "Our group has earlier shown that G-CSF reduces the disease severity, delays the mortality of severe alcoholic hepatitis (SAH) patients, and mobilizes bone marrow-derived CD34+ cells in acute-on-chronic liver failure (ACLF) patients for hepatic regeneration." (PMID 35720398, 2022). "The plasma levels and EVs of cytokeratin-18 fragments (M30 and M65) are reliable non-invasive markers of alcoholic hepatitis High levels of CD34+ and ASGPR1+ EVs can be used as markers of non-response to corticosteroid therapy in severe alcoholic hepatitis." (PMID 36555854, 2022). "Pre-therapy levels of CD34+ and ASGPR+ microvesicles are reliable non-invasive markers of steroid nonresponse and mortality in patients with severe alcoholic hepatitis." (PMID 36555854, 2022).
alopecia (3 papers, 2020 to 2024). Hair loss usually from the scalp. "Stabilization of β-catenin in CD34+ cells led to senescence of mesenchymal cells and the formation of progressive alopecia." (PMID 35478971, 2022). "Indeed from this, we further denoted the unique biological properties of CD34+ hfDSCs, making it a highly promising potential molecular target for regulating HF senescence with clinical applications towards cell-based approaches for alopecia treatment." (PMID 35478971, 2022).
amyotrophic lateral sclerosis (3 papers, 2019 to 2024). Amyotrophic lateral sclerosis (ALS) is a neurodegenerative disease characterized by progressive muscular paralysis reflecting degeneration of motor neurons in the primary motor cortex, corticospinal tracts, brainstem and spinal cord. "Neu_c4_RSAD2, Isg15_Neu, IFITM2_Neu, CCL6_Neu, and Cd34_mNeu were assessed as specific panels (OER10 > 83%, data was not shown) in anti-NMDA receiver encephalitis, which was significantly different from that of amyotrophic lateral sclerosis." (PMID 38319415, 2024).
androgenetic alopecia (3 papers, 2012 to 2021). "The bald scalps of men with androgenetic alopecia lack CD200-rich, CD34-positive hair follicle progenitor cells, and have a defect in conversion of hair follicle stem cells to progenitor cells, which play a role in the pathogenesis of androgenetic alopecia." (PMID 22506014, 2012). "K15 was found at normal levels of non-productive hair follicles of bald scalp from men with androgenic alopecia, but CD34 and CD200 were markedly diminished suggesting a failure of the conversion from K15-positive stem cells to CD34- and CD200-positive hair progenitor cells." (PMID 23799033, 2013).
Angiofibroma (3 papers, 2012 to 2025). A benign neoplasm of fibrous tissue in which there are numerous small and large, frequently dilated, vascular channels. "An intriguing possibility was indicated by the discovery of a small subset of stromal spindle cells expressing CD133 and CD34 in angiofibromas." (PMID 23209640, 2012). "They show variable positivity for CD34 and can be EMA positive; however, the absence of hypervascularity aids in this differentiation The combination of histological key features, immunohistochemistry, and clinical presentation can aid in the diagnosis of Cellular Angiofibroma." (PMID 40626172, 2025).
autism (3 papers, 2007 to 2024). Persistent deficits in social interaction and communication and interaction as well as a markedly restricted repertoire of activity and interest as well as repetitive patterns of behavior. "In this paper we examine two pathologies associated with autism – hypoperfusion to the brain and immune dysregulation – and propose a novel treatment: the administration of CD34+ umbilical cord cells and mesenchymal cells." (PMID 17597540, 2007). "We propose a Phase I/II open labeled study investigating combination of cord blood expanded CD34+ cells together with mesenchymal stem cells for the treatment of autism." (PMID 17597540, 2007). "We propose the combined use of MSC and cord blood CD34+cells may be useful in the treatment of autism." (PMID 17597540, 2007). "Given the ability of umbilical cord blood CD34+ cells to induce angiogenesis in areas of cerebral hypoperfusion, some authors have proposed that this type of cell may be useful for the treatment of autism." (PMID 39061976, 2024). "Given the potency of cord blood CD34+ cells to promote angiogenesis in ischemic areas, the CBMNC may be useful for the improvement of the cerebral hypoperfusion and hypoxia that has been suggested to occur in the brains of individuals with autism." (PMID 23978163, 2013).
benign prostatic hyperplasia (3 papers, 2022 to 2026). A non-cancerous nodular enlargement of the prostate gland. "CD34 overexpression is specifically associated with the development of stromal nodules in benign prostatic hyperplasia." (PMID 38778357, 2024). "In addition, benign prostatic hyperplasia showed a significantly lower pattern for the CD34- cell population reported to control cases (32.69 ± 11.30 vs. 45.25 ± 0.52, p < 0.01), which characterized the tumoral cells’ adhesion to endothelial cells from larger veins and arteries." (PMID 35884977, 2022).
cavernous hemangioma (3 papers, 2013 to 2022). A hemangioma characterized by the presence of cavernous vascular spaces. "A positive reaction with HHV-8, CD31, CD34, and D2-40 monoclonal antibodies was identified at both cavernous hemangioma-like areas and in immature vascular structures." (PMID 24187557, 2013). "Immunohistochemical examinations of lesions from both cases showed a strong reaction with endothelial markers (CD31, CD34, and D2-40) and HHV-8 (LNA-1) both in endothelia of the cavernous hemangioma-like vascular structures and at the areas of early-stage KS." (PMID 24187557, 2013). "Immunohistochemical examination of lesions of both cases revealed a strong positive reaction with endothelial markers (CD31, CD34, and D2-40) and HHV-8 (LNA-1) in both endothelial lining of cavernous hemangioma-like vascular structures and at areas of typical early-stage KS." (PMID 24187557, 2013).
chronic pancreatitis (3 papers, 2015 to 2024). A chronic inflammatory process causing damage and fibrosis of the pancreatic parenchyma. "Stromal cells in 91.7% (22/24) of cases showed CD34 positivity, but this can also be detected in the stroma of chronic pancreatitis, which complicates the interpretation of biopsy results." (PMID 32448918, 2020). "Cluster F2 was characterized by expression of markers implicated with inflammatory processes in fibroblasts, such as CD34 and RSPO3, congruent with this cluster predominantly found in patients with chronic pancreatitis." (PMID 39485038, 2024).
colorectal tumor (3 papers, 2015 to 2023). "As an example, a reduction in CD34+ stromal cells has been reported in colorectal tumour stroma and peritumoral inflammatory tissue." (PMID 25283476, 2015).
cystitis (3 papers, 2017 to 2024). Inflammation of the urinary bladder. "Group A had 105 patients (100 with UC; 5 with cystitis); group B had 55 patients (all with high-grade UC; D2-40 and CD34 immunohistochemical stains performed on each block)." (PMID 38396472, 2024). "No phenotypic change was observed here as CYP-induced cystitis progressed, and the prominent increase in CD34-ir during the intermediate and chronic inflammatory process further suggests that proliferating cells cannot be considered myofibroblasts." (PMID 28698872, 2017).